TSPAN6 (tetraspanin 6)
Synonyms: Tspan-6; TM4SF6; T245
Tractability: Antibody: UniProt predicts a signal peptide or a membrane-spanning region; its Gene Ontology location is reachable by antibodies, with medium confidence. PROTAC: ubiquitination databases record sites on it; its protein half-life has been measured.
Gene: Protein-coding gene on chromosome X (100,627,108 to 100,639,991, reverse strand). Ensembl gene ENSG00000000003.
Subcellular location: Membrane
Subcellular location (Human Protein Atlas): Cell Junctions; Cytosol; Nucleoli fibrillar center
Gene Ontology:
Molecular function: protein binding
Biological process: negative regulation of canonical NF-kappaB signal transduction; negative regulation of cytoplasmic pattern recognition receptor signaling pathway; positive regulation of canonical NF-kappaB signal transduction
Cellular component: extracellular exosome; plasma membrane; membrane
Homologues: Orthologues: chimpanzee TSPAN6 (100% identical), pig TSPAN6 (97% identical), rabbit TSPAN6 (96% identical), dog TSPAN6 (95% identical), rat Tspan6 (93% identical), mouse Tspan6 (93% identical), guinea pig TSPAN6 (91% identical), tropical clawed frog tspan6 (73% identical), zebrafish tspan6 (58% identical). Paralogues in human: TSPAN7 (59% identical), CD151 (29% identical), TSPAN17 (28% identical), CD63 (27% identical), TSPAN11 (27% identical), TSPAN5 (27% identical), TSPAN33 (27% identical), TSPAN14 (26% identical), TSPAN8 (26% identical), TSPAN9 (26% identical), TSPAN1 (25% identical), TSPAN18 (25% identical), and 20 more.
Diseases named in the same sentence as TSPAN6 in open-access papers:
TSPAN6 is named in the same sentence as 33 diseases in open-access papers, as found by Europe PMC text mining. Sharing a sentence is not in itself a finding about the gene and the disease. The quoted sentences say what the papers report.
colorectal cancer (7 papers, 2021 to 2025). A primary or metastatic malignant neoplasm that affects the colon or rectum. "The proposed mechanism for the role of tetraspanin 6 in colorectal cancer progression includes the activation of the EGF‐dependent signaling pathway through loss of tetraspanin 6 expression." (PMID 39031113, 2024). "Conversely, down-regulation (or loss) of Tspan6 in colorectal cancers results in the redistribution of the tmTGF-α−syntenin-1 complex to the EVs." (PMID 34521767, 2021). "Studies carried out in an early stage colorectal cancer murine model have suggested that suppression of tetraspanin 6 expression increases the incidence and size of adenomas." (PMID 39031113, 2024). "The expression of TSPAN6 is frequently decreased or even lost in colorectal cancer tissues, and correlates with favorable survival." (PMID 36941633, 2023). "TSPAN6 deletion facilitates colorectal cancer development and results in the activation of EGF-dependent signaling pathways through increased production of the transmembrane form of TGF-α (tmTGF-α) associated with extracellular vesicles." (PMID 36941633, 2023). "To examine the involvement of Tspan6 in the neoplastic transformation of gastrointestinal tissues, we crossed Tspan6 knockout (Tspan6−/−) animals with APCmin/+ mice, a well-characterized model for colorectal cancer." (PMID 34521767, 2021). "Using a combination of in vitro and in vivo assays, we demonstrate that Tspan6 functions as a tumor suppressor in colorectal cancer (CRC) by attenuating the epidermal growth factor receptor (EGFR)–based signaling axis." (PMID 34521767, 2021). "A recent study has revealed that TSPAN6 also plays a tumor suppressor role in colorectal cancer, but whether TSPAN6 has a tumor suppressor role in additional cancer types, apart from pancreatic, lung and colorectal, needs to be explored in future experiments." (PMID 35184157, 2022). "To extend our findings linking Tspan6 and EGFR-dependent signaling in colorectal cancer, we investigated whether the expression of Tspan6 can predict a response to the EGFR-targeting therapies in vivo." (PMID 34521767, 2021). "Additionally, recent findings suggest that TSPAN6 functions as a tumor suppressor in colorectal cancer and may serve as a prognostic biomarker in glioma patients." (PMID 40299352, 2025). "Furthermore, TSPAN6 in colorectal cancer cells might decrease the TGF-α content in the EVs, which could activate EGFR signaling in target cells." (PMID 36941633, 2023). "TSPAN6, a tetraspanin family member, is a tumor suppressor protein that interferes with TGF-α signaling in colorectal cancer." (PMID 38283944, 2023). "In addition, TSPAN6 deletion promotes colorectal cancer organoid growth in an EV-dependent manner, as EV-depleted media could not support proliferation and viability of TSPAN6-expressing organoids." (PMID 36941633, 2023).
adenoma (4 papers, 2021 to 2024). A neoplasm arising from the epithelium. "Tetraspanin 6 (Tspan6) deletion in Apcmin/+ mice accelerates adenoma formation through autocrine activation of EGFR mediated by EV-associated secretion of the transmembrane form of TGF-α." (PMID 38741166, 2024). "Proliferation, as detected by Ki67 staining, was significantly enhanced in hyperplastic regions, as well as in early (4 weeks after Ad-Cre inhalation) adenomas and adenocarcinomas from Tspan6−/yKrasG12D mice compared to their Tspan6+/yKrasG12D littermates." (PMID 35184157, 2022). "Eight weeks after Ad-Cre inhalation, we again observed significantly more hyperplastic regions as well as increased numbers of adenomas in Tspan6−/yKrasG12D mice." (PMID 35184157, 2022). "Tspan6fl/yKrasG12D mice also harbored significantly more hyperplastic lesions and increased numbers of adenomas and adenocarcinomas as compared to their Tspan6-expressing littermates." (PMID 35184157, 2022). "Immunohistochemistry for phospho-EGFR revealed markedly increased phospho-EGFR staining in Tspan6 mutant lung tumors, in particular in the hyperplastic regions and adenomas." (PMID 35184157, 2022). "Histological analysis indicated that all lesions in APCmin/+ and APCmin/+/Tspan6−/− mice could be classified as adenomas." (PMID 34521767, 2021). "Here, we demonstrate that the deletion of a poorly studied tetraspanin protein Tspan6 in Apcmin/+ mice, a well-established model for premalignant CRC, resulted in increased incidence of adenoma formation and tumor size." (PMID 34521767, 2021).
epilepsy (4 papers, 2017 to 2023). A brain disorder characterized by episodes of abnormally increased neuronal discharge resulting in transient episodes of sensory or motor neurological dysfunction, or psychic dysfunction. "Deletions at TSPAN6 cause epilepsy female-restricted with intellectual disability." (PMID 33343629, 2020). "Genomic deletions including the Tspan6 gene have been described in two female patients with epilepsy and intellectual disability." (PMID 28207852, 2017). "Deletions of Tetraspanin 6 (Tspan6) gene, a member of the tetraspanin family, have been reported in patients with Epilepsy Female-restricted with Mental Retardation (EFMR)." (PMID 28207852, 2017).
Intellectual disability (4 papers, 2017 to 2023). "Further investigation is required to understand the molecular mechanism underlying Tspan6-dependent effect on synaptic transmission and whether this effect is partially responsible for the seizures and intellectual disability described in patients." (PMID 28207852, 2017).
Alzheimer disease (3 papers, 2017 to 2020). A progressive, neurodegenerative disease characterized by loss of function and death of nerve cells in several areas of the brain leading to loss of cognitive function such as memory and language. "We focused the study on hippocampal CA1 pyramidal neurons as Tspan6 is highly expressed here, and changes in spine density in this brain region have been associated with cognitive diseases such as Alzheimer disease and Rett syndrome." (PMID 28207852, 2017). "Guix and colleagues reported that TSPAN6 was increased in Alzheimer’s disease brains and promoted Aβ-peptide accumulation by affecting the autophagosome–lysosomal pathway and slowing down the degradation of Amyloid precursor protein (APP)–C-terminal fragments." (PMID 33343629, 2020). "Given that several studies show that TSPAN6 transcripts increase in late Braak stages of the Alzheimer’s disease brain, we first overexpressed a myc-tagged form of TSPAN6 (myc-TSPAN6) in human embryonic kidney (HEK293) cells." (PMID 28279219, 2017).
breast carcinoma (3 papers, 2024 to 2025). "Breast cancer cells overexpressing tetraspanin-6 (TSPAN6) promote B lymphocyte infiltration of tumors by driving the accumulation of oxysterol ligands, such as 25-hydroxycholesterol (25HC) and 27HC, within cell-derived extracellular vesicles." (PMID 40270603, 2025). "In breast cancer, tetraspanin 6 has been shown to possibly enhance the invasion of B lymphocytes into the tumor." (PMID 39031113, 2024). "Following the discovery that Tspan6 enhances the chemoattractive potential of breast cancer cells for B lymphocytes in an EV-dependent manner, it was shown that this effect relied on the function of liver X receptors, which are nuclear receptors for oxysterols, in B cells." (PMID 40135387, 2025). "Current research suggests that tetraspanin 6 may have anticancer effects and may play a role in the transformation and progression of colorectal, lung, pancreatic, and breast cancers." (PMID 39031113, 2024). "However, contrasting results were observed in breast cancer MCF7 cells, where Tspan6 limited EV release by promoting syndecan-4-dependent syntenin lysosomal degradation." (PMID 40135387, 2025). "Further complicating the picture, transfection of Tspan6 in another breast cancer cell line did not alter EV release, and organoids derived from APC mutant Tspan6 KO mice produced similar amounts of EVs as those expressing Tspan6." (PMID 40135387, 2025).
pancreatic cancer (3 papers, 2022 to 2025). "Studies have shown that reduced TSPAN6 expression is associated with poor survival in lung and pancreatic cancer cohorts exhibiting mesenchymal traits." (PMID 40299352, 2025). "Together these data indicate that low TSPAN6 expression levels correlate with lung and pancreatic cancer EMT signatures and also with poor survival in these cancer patients." (PMID 35184157, 2022). "Finally, low TSPAN6 expression correlates with poor prognosis of patients with lung and pancreatic cancers with mesenchymal morphology." (PMID 35184157, 2022). "Moreover, our analysis of human lung and pancreatic cancer cohorts shows a correlation of low TSPAN6 expression with cancers with an EMT signature and with poor patient survival." (PMID 35184157, 2022). "Furthermore, we show in lung and pancreatic cancer cohorts that low TSPAN6 expression correlates with poor survival in cancers with mesenchymal features." (PMID 35184157, 2022). "Thus, overexpression of TSPAN6 in the two K-RAS-activating mutant human pancreatic cancer cell lines, PANC1 and MIA PaCa2, impaired proliferation and migration in vitro and significantly reduced tumor growth and metastasis in vivo." (PMID 35184157, 2022). "In mouse orthotopic transplantation experiments, Tspan6 knockdown promotes tumorigenesis of H-RasV12-transformed mouse mammary epithelial (EpRas) cells, and overexpression of TSPAN6 abrogates the tumorigenic potential of K-Ras activating mutant human pancreatic cancer cells." (PMID 35184157, 2022). "Furthermore, our results show that overexpression of TSPAN6 impairs cell proliferation and invasion of pancreatic tumor cells in vitro and abrogates tumor growth and metastatic spread in orthotopic tumor implants in vivo." (PMID 35184157, 2022). "In addition to lung and pancreatic cancer, mining of various databases, including TCGA, revealed mutations, deletions, and copy number variations of TSPAN6 in multiple human cancers (not shown)." (PMID 35184157, 2022). "Moreover, TSPAN6 overexpression reduced EGF-dependent invasion using transwell migration assays; in vitro scratch assays further confirmed that TSPAN6 overexpression in these K-RAS activating mutant pancreatic cancer cells leads to impaired epithelial sheet migration." (PMID 35184157, 2022). "Here we show that TSPAN6 suppressed tumor growth and metastatic dissemination of human RAS activating mutant pancreatic cancer xenografts." (PMID 35184157, 2022). "Functionally, we found that Dox-induced TSPAN6 expression in both MIA PaCa2 and PANC1 pancreas cancer cells decreased proliferation at baseline." (PMID 35184157, 2022). "Thus, TSPAN6 constitutes an evolutionary conserved bona fide suppressor of oncogenic RAS-driven tumor growth and invasion/metastasis in human pancreatic cancer cells, human and mouse mammary epithelial cells and mouse lung tumors." (PMID 35184157, 2022). "We found that low expression of TSPAN6 correlated with pancreatic adenocarcinomas with an EMT signature (Panc-exoc and Panc-Qm) relative to those with an epithelial signature (Panc-epith) in two pancreatic cancer cohorts." (PMID 35184157, 2022). "Importantly, low TSPAN6 expression was correlated with an EMT signature and poor survival of human patients with non-small cell lung and pancreatic cancers, indicating that TSPAN6 functions as a tumor suppressor in human epithelial cancers." (PMID 35184157, 2022). "Next, to determine the role of elevated expression of TSPAN6 in suppressing RAS-mutant human cancers in vivo, we used a doxycyclin (Dox)-inducible Tet ON/OFF switch to regulate TSPAN6 expression in two human K-RAS activating mutant pancreatic cancer cell lines, MIA PaCa2 and PANC1." (PMID 35184157, 2022). "Moreover, induction of TSPAN6 in human pancreatic cancer cells inhibits EGFR-induced expression of the EMT markers Vimentin and N-Cadherin, as well as the critical EMT transcription factor Slug, thereby linking TSPAN6 to the inhibition of EGFR-mediated EMT in human tumor cells." (PMID 35184157, 2022).
glioma (2 papers, 2024 to 2025). A benign or malignant brain and spinal cord tumor that arises from glial cells (astrocytes, oligodendrocytes, ependymal cells). "We established RNA sequence to compare the mRNA expression between clinical glioma tumor tissue and adjacent normal tissue, TSPAN6 was the only gene among TSPANs which was listed on TOP 20 upregulated genes in glioma." (PMID 38725860, 2024). "Meanwhile, TSPAN6 expression was a potential prognostic biomarker for glioma patients." (PMID 38725860, 2024). "This study also firstly demonstrated that TSPAN6 was remarkably high in glioma tumor tissues compared to corresponding non-tumor tissues using pan-cancer analysis based on TCGA database." (PMID 38725860, 2024).
lung carcinoma (2 papers, 2022 to 2024). "In addition, decreased tetraspanin 6 expression is associated with shorter survival in patients with pancreatic or lung cancer." (PMID 39031113, 2024). "Importantly, by generating Tspan6 whole-body mutant mice and a conditional Tspan6floxed allele, we provide definitive evidence that loss of Tspan6 markedly enhances the initiation as well as malignant progression of oncogenic Kras-driven lung cancer in a tumor cell autonomous manner." (PMID 35184157, 2022). "Recently, studies performed in mouse models have indicated that tetraspanin 6 acts as a tumor suppressor protein in pancreatic and lung cancers." (PMID 39031113, 2024). "In conclusion, our genetic data show that Tspan6 exerts a cell autonomous function in suppressing KRasG12D-driven initiation and progression of lung cancer." (PMID 35184157, 2022). "To therefore test whether the effects of Tspan6 on KrasG12D-induced lung cancer are cell autonomous to the transformed lung epithelium, we generated mice that carry a Tspan6floxed allele." (PMID 35184157, 2022).
aortic stenosis (1 paper, 2026). Aortic valve stenosis is a aortic valve disease caused by the incomplete opening of the aortic valve. "We also observed two signals on the X chromosome, in loci near NDP (for the gradient-based measures) and near TSPAN6 (for AVA), both of which have not been described for aortic stenosis or aortic valve disease before." (PMID 41419685, 2026).
cognitive defects (1 paper, 2017). "In addition, the impaired LTP observed in Tspan6 KO mice could also support the cognitive defects shown in the patients." (PMID 28207852, 2017).
Down syndrome (1 paper, 2017). "By co-expressing the Rab5Q79L mutant with TSPAN6 in HEK293 cells, we observe exacerbated enlarged Rab5-positive vesicles similar to those seen in neurons generated from induced pluripotent stem cells from AD patients and Down syndrome fibroblasts." (PMID 28279219, 2017).
early infantile epileptic encephalopathy-9 (1 paper, 2020). "More recently, the deletion of the tetraspanin protein TSPAN6 was identified in patients with early infantile epileptic encephalopathy-9 (EIEE9), but a role for TSPAN6 in spine remodeling could not be established." (PMID 32655390, 2020).